KIF11 (kinesin family member 11)
Description:
Motor protein required for establishing a bipolar spindle and thus contributing to chromosome congression during mitosis. Required in non-mitotic cells for transport of secretory proteins from the Golgi complex to the cell surface.
Synonyms: EG5; KNSL1; TRIP5; HKSP; MCLMR
Tractability: Small molecule: a drug acting on it is in phase 2 or 3 trials; a structure with a bound ligand is known; a high-quality ligand is known; it has a high-quality binding pocket; it belongs to a druggable protein family. PROTAC: UniProt records ubiquitination sites on it; ubiquitination databases record sites on it; a small molecule that binds it is known.
Target class: Other cytosolic protein
Chemical probes: CK0106023, DOCETAXEL, ISPINESIB, PD081273, PD081628, PD081819, PD081829, PD081913, PD082283, PD082407, PD082413, PD082432, PD082712, PD082899, PD083111, PD083236, PD083334, PD083504, PD083518, PD083769, and 14 more
Gene: Protein-coding gene on chromosome 10 (92,574,105 to 92,655,395, forward strand). Ensembl gene ENSG00000138160.
Subcellular location: Cytoplasm; Cytoplasm, cytoskeleton, spindle pole
Subcellular location (Human Protein Atlas): Cytosol; Mid piece; Basal body; End piece; Mitotic spindle; Principal piece; Vesicles
Pathways (Reactome):
Hemostasis: Kinesins
Immune System: MHC class II antigen presentation
Vesicle-mediated transport: COPI-dependent Golgi-to-ER retrograde traffic
Gene Ontology:
Molecular function: protein binding; protein kinase binding; microtubule motor activity; plus-end-directed microtubule motor activity; ATP binding; microtubule binding
Biological process: mitotic spindle assembly; regulation of mitotic centrosome separation; spindle organization; mitotic cell cycle; mitotic spindle organization; spindle elongation; microtubule-based movement; spindle assembly
Cellular component: cytoplasm; cytosol; membrane; microtubule; protein-containing complex; spindle; spindle microtubule; spindle pole; kinesin complex; mitotic spindle; nucleus
Genetic constraint (gnomAD): Loss-of-function variants: 3 observed, 42.1 expected, observed/expected ratio (o/e) 0.0713, 90% interval 0.031 to 0.18. The upper end of that interval is the gene's LOEUF score, 0.18, which puts it in group 1 of 6, group 1 being the genes least tolerant of losing a copy. Missense variants: 355 observed, 525.7 expected, observed/expected ratio (o/e) 0.68, 90% interval 0.62 to 0.74. Synonymous variants: 180 observed, 191.97 expected, observed/expected ratio (o/e) 0.94, 90% interval 0.83 to 1.06.
Gene-disease validity (ClinGen):
ClinGen rates the evidence that KIF11 causes each of these diseases.
microcephaly with or without chorioretinopathy, lymphedema, or intellectual disability (autosomal dominant): Definitive. A microcephaly caused by a mutation in KIF11 gene and follows autosomal dominant inheritance.
Homologues: Orthologues: chimpanzee KIF11 (99% identical), macaque KIF11 (98% identical), rabbit KIF11 (88% identical), pig KIF11 (87% identical), dog KIF11 (83% identical), guinea pig KIF11 (83% identical), mouse Kif11 (79% identical), rat Kif11 (78% identical), tropical clawed frog kif11 (56% identical), zebrafish kif11 (49% identical), Drosophila melanogaster Klp61F (31% identical), Caenorhabditis elegans bmk-1 (30% identical), and 2 more. Paralogues in human: KIF13B (22% identical), KIF13A (22% identical), KIF21B (22% identical), KIF5B (22% identical), KIF1A (22% identical), KIF5C (22% identical), CENPE (22% identical), KIF5A (22% identical), KIF1B (21% identical), KIF21A (21% identical), KIF16B (21% identical), KIF15 (21% identical), and 29 more.
Diseases named in the same sentence as KIF11 in open-access papers:
KIF11 is named in the same sentence as 181 diseases in open-access papers, as found by Europe PMC text mining. Sharing a sentence is not in itself a finding about the gene and the disease. The quoted sentences say what the papers report.
breast carcinoma (56 papers, 2014 to 2025). "In the other studies in breast cancer, overexpression of KIF11 and KIF14 has been associated with worse overall survival, indicating their potential as prognostic biomarkers." (PMID 40075652, 2025). "According to an Oncomine analysis of GEO and TCGA databases, KIF11 is a proto-oncogene associated with breast cancer and is significantly associated with poor prognosis." (PMID 34675265, 2021). "Higher KIF11 mRNA levels and lower miR‐30a were significantly associated with poor survival of breast cancer patients." (PMID 32346924, 2020). "In addition, we observed that 40 and 10 breast cancer cell-lines samples show the highest connectivity loss score of KIF11 and AURKA, respectively." (PMID 38622359, 2024). "Expression of KIF11 and miR‐30a is associated with the development and outcome of breast cancer." (PMID 32346924, 2020). "Since NES of KIF11 was associated with poor prognosis, poor differentiation, and metastasis of breast cancer, the expression of KIF11 could be related to poor outcomes in breast cancer." (PMID 32346924, 2020). "Thus, our data indicated that RRM2 might contribute to breast cancer progression and drug insensitivity associated with KIF11 expression." (PMID 30898978, 2019). "According to previous studies, overexpression of KIF11 was shown in breast cancer, epithelial ovarian cancer, clear cell renal cell carcinoma, colorectal cancer, hepatocellular carcinoma, pancreatic adenocarcinoma, oral cancer, and lung cancer." (PMID 40075652, 2025). "KIF14 or KIF11 are overexpressed in multiple tumor types including ovarian cancer, breast cancer, and EC." (PMID 40075652, 2025). "Breast cancer patients with higher KIF11 expression were resistant to endocrine therapy and were resistant to chemotherapy with lower KIF11 expression." (PMID 36742345, 2022). "For example, Ispinesib, a KIF11 inhibitor, was evaluated in a phase I clinical trial in breast cancer, although the specific inhibitors for KIF4A and KIF18B are still limited." (PMID 36499051, 2022). "In a study that examined the association between members of the kinesin family and breast cancer, KIF23 and KIF11 were found to be associated with poor prognosis." (PMID 34675265, 2021). "Pei and collaborators (2019) showed that self-renewal of breast cancer cells is enhanced by endogenous KIF11 through activating Wnt/β-catenin signaling pathway contributing to the breast cancer stem cell features." (PMID 34548908, 2021). "In this work we propose the substitution of the taxane (paclitaxel) in the AC-T therapeutic breast cancer regimen with a KIF11 inhibitor, in the hope of preserving antitumoral activity while reducing toxicity." (PMID 34548908, 2021). "As KIF11 is involved with breast cancer development, drug resistance and poor prognosis, the control of its expression can improve results obtained with chemotherapy, being responsible for better outcomes." (PMID 34548908, 2021). "Although it has been reported that KIF11 is overexpressed in malignant tumors including gastric cancer, malignant mesothelioma, breast cancer, and glioblastoma, there are limited reports relevant to the function of KIF11 in LUAD." (PMID 33968780, 2021). "The correlation between ID1 and KIF11 gene expression and relapse free-survival of breast cancer patients was analyzed by the KM Plotter database." (PMID 32911668, 2020). "In this study, we demonstrated that KIF11 is highly expressed in breast cancer cell lines and closely related to poor differentiation and aggressive phenotypes in breast cancer patients." (PMID 32346924, 2020). "Studies have shown that KIF11 is overexpressed in many cancers, such as gastric cancer, breast cancer, oral cancer, renal cell, and astrocytic cancers." (PMID 33061942, 2020). "Inhibition of KIF11 by small‐hairpin RNA significantly reduced the proliferation and invasion capabilities of the breast cancer cells." (PMID 32346924, 2020).
breast carcinoma (continued). "Recently, KIF11 has been reported to be a novel potential candidate prognostic biomarker or therapeutic target in human cancers including breast cancer, ovarian cancer, oral cancer, peripheral nerve sheath tumors, and lung cancer." (PMID 33376723, 2020). "Further stratified Kaplan‐Meier analysis with the pooled data explored that KIF11 mRNA levels were significantly associated with poor OS and poor DFS in not only ER‐negative but also in ER‐positive breast cancers." (PMID 32346924, 2020). "Taken together, we demonstrate a critical role of KIF11 in promoting invasion and predicting poor prognosis in breast cancer patients." (PMID 32346924, 2020). "In the present study, we investigated the role of KIF11 in the tumorigenesis and treatment of breast cancer and the possible role of miR‐30a in the regulation of KIF11 in this process." (PMID 32346924, 2020). "Undoubtedly, extensive investigations are required to illuminate the elaborate mechanism of KIF11 in the development and regulation of breast cancer, and in‐depth studies are also needed to uncover the interactions between KIF11 and miR‐30a." (PMID 32346924, 2020). "A recent study has shown the in vitro and in vivo decrease in cellular proliferation, induction of G2/M cell cycle arrest and increased apoptosis of human breast cancer cells upon RNAi mediated silencing of KIF11." (PMID 32752229, 2020). "Studies by our group and others have already reported that Id1 marks a chemoresistant breast cancer cell in cancers such as hepatocarcinomas, and the Kif11 pathway has been targeted in the treatment of docetaxel-resistant TNBC cells." (PMID 32911668, 2020). "microRNA was predicted targeting KIF11 through sequence alignment in microRNA.org and confirmed by coexpression analysis in human breast cancer samples." (PMID 32346924, 2020). "A population study also validated that chemotherapy and radiotherapy significantly improved survival in early‐stage breast cancer patients with low KIF11 expression levels." (PMID 32346924, 2020). "Second, the OS and DFS in breast cancer databases were significantly lower in high‐KIF11 breast cancer than in low‐KIF11 breast cancer." (PMID 32346924, 2020). "To explore the role of KIF11 in the development of breast cancer, we analyzed mRNA expression of KIF11 in both cell lines and the GSE70947 dataset." (PMID 32346924, 2020). "KIF11 can also be employed as a therapeutic target and can serve as a biomarker for selecting chemotherapy and radiotherapy in breast cancer treatment." (PMID 32346924, 2020). "Based on integrated bioinformatic analysis, the present study has identified 321 DEGs and six hub genes (CDK1, CCNA2, TOP2A, CCNB1, KIF11, and MELK) that are associated with breast cancer tumorigenesis and progression." (PMID 31428132, 2019). "The co-expression profile of RRM2 was identified with a large cluster of 1802 genes across 61 breast carcinomas, and KIF11 is a principal correlated gene." (PMID 30898978, 2019). "KIF11, a molecular motor protein involved in mitosis, was critical for proliferation and self-renewal in chemoresistant breast cancer cells." (PMID 30898978, 2019). "KIF11 mRNA was significantly higher in the tumor samples resected from the breast cancer patients and much lower in the matched normal tissues (P<0.001)." (PMID 29190901, 2017). "We further analyzed KIF11 expression levels across different breast cancer subtypes in TCGA (The Cancer Genome Atlas) database, the results revealed that high KIF-11 expression correlated with the more aggressive TNBC subtype, compared to non-TNBC tumors." (PMID 29190901, 2017). "As already shown in breast cancer, we also find several members of the Kinesin protein family (KIF11, KIF15, KIF23, KIF2C and KIFC1) to be upregulated in patients with high expression of ATAD2." (PMID 26308378, 2015).
breast carcinoma (continued). "Various clinicopathological features (e.g., tumor size and pathological stage and TNM stages) are significantly associated with overexpressed KIF11, which has been revealed in a series of cancers types, such as ACC, NSCLC, CRC, prostate cancer (PCa), and breast cancer, among others." (PMID 38672404, 2024). "Consequently, the protein level of KIF11 is decreased to suppress the viability of breast cancer cells." (PMID 38672404, 2024). "Additionally, TRAF4 decreases the level of SMAD-specific E3 ubiquitin protein ligase family member 2 (SMURF2) and inhibits the polyubiquitination of KIF11 to promote breast cancer cell proliferation." (PMID 38672404, 2024). "In breast cancer, negative regulation between KIF11 and miR-30a has been elucidated." (PMID 38672404, 2024). "Furthermore, KIF11 is upregulated in various human cancers, including bladder cancer, renal clear cell carcinomas, prostate carcinomas, meningiomas, breast cancer, and gastric ccancer." (PMID 35669725, 2022). "In population-based studies, TPMT, TOR2A, KIF11, and EIF5A were reported to be associated with prognosis in other tumours, such as childhood acute lymphoblastic leukaemia, ovarian cancer, breast cancer, and colorectal cancer." (PMID 35421138, 2022). "In this regard, it was previously indicated that knockdown of KIF11 kinesin was able to abrogate the chemotactic migration of breast carcinoma cells and that the allosteric inhibition of Eg5 kinesin by dimethylenastron suppressed pancreatic tumor cell movement and invasion." (PMID 35312942, 2022). "These considerations imply that KIF11 inhibitors may represent a promising strategy to be used as adjuvant therapy in breast cancer treatment regimen and may improve TNBC patients’ outcomes showing considerably fewer side effects." (PMID 34548908, 2021). "The overexpression of KIF11 affected the survival of patients with breast cancer." (PMID 34582664, 2021). "Interestingly, CHK1 inhibition showed the single-agent antitumor activity in ER+/PR+/HER2- breast cancer which was mediated by the cyclin dependent kinase inhibitor 1A (p21), kinesin family member 11 (Eg5) and cell surface death receptor (Fas)." (PMID 32210727, 2020). "By GSEA analysis, we verified that KIF11 enrichment occurs in breast cancer." (PMID 32346924, 2020). "It was confirmed that KIF11 expression significantly impacted the poor survival of breast cancer." (PMID 32346924, 2020). "Moreover, KIF11 was identified as an oncogene in breast cancer through prompting cell proliferation, colony formation, cell migration while inhibiting cell apoptosis." (PMID 32439830, 2020). "Analysis results showed that mRNA expression levels of KIF11 were significantly associated with the younger patient, lower ER levels, bigger tumor size, lymph node, and higher grade of breast cancer in none‐TCGA and TCGA datasets." (PMID 32346924, 2020). "Our findings highlight that miR‐30a and KIF11 could be employed as promising prognostic biomarkers and therapeutic targets for breast cancers." (PMID 32346924, 2020). "Here, we hypothesize that KIF11 might be a therapeutic target of breast cancer and regulated by miR‐30a." (PMID 32346924, 2020). "Meanwhile, downregulation of KIF11 could enhance the cytotoxicity of adriamycin in breast cancer cell lines MCF‐7 and MDA‐MB‐231." (PMID 32346924, 2020). "RRM2 could be used as a predictive biomarker for prognosis of breast cancer with co-expressed KIF11 gene." (PMID 30898978, 2019). "Similarly, KIF11 inhibition has been shown to reduce breast cancer growth, migration, and invasion." (PMID 41487287, 2025). "Inhibition of KIF11 by shRNA could improve the efficacy of adriamycin on breast cancer cells." (PMID 32346924, 2020). "Furthermore, our validation in vitro study and clinical relevance analysis suggest that miR‐30a could be a negative regulator of KIF11 in breast cancer development." (PMID 32346924, 2020).
breast carcinoma (continued). "Although in the course of our research, one study has discussed the function of KIF11 in breast cancer, whether KIF11 is a potential therapeutic target for breast cancer remains unclarified currently, and the transcriptional regulation on KIF11 also needs to be elucidated." (PMID 32346924, 2020). "Therefore, KIF11 is a potential therapeutic target of breast cancer." (PMID 32346924, 2020). "miR‐30a could specifically interact with KIF11 and suppress its expression in breast cancer." (PMID 32346924, 2020). "In breast cancer, the RNF20/40 ubiquitin ligase complex monoubiquitinates and stabilizes KIF11 at K745 to promote breast carcinogenesis." (PMID 38672404, 2024). "A cancer dependency map (depmap.org) further highlighted KIF11, AURKB, RACGAP1 and TPX2 as genes with essential effects in 47 breast cancer cell lines." (PMID 37835564, 2023). "Results revealed that KIF11, AURKB, TPX2 and KIFC1 are essential genes whose depletion in both breast cancer cell lines impacts cell viability." (PMID 37835564, 2023). "Samples with high expression (red line) have lower percent survival and lifetime than samples with low KIF11 expression (blue line) likewise, with the overexpression of AURKA protein in breast cancer patients." (PMID 34582664, 2021). "Ispinesib, a KIF11-targeted inhibitor, was the first KIF-inhibitor that was evaluated both safety and efficacy in breast cancer in phase I clinical study." (PMID 32322170, 2020). "Considering the identification of the upregulated KIF11 in breast cancer, it may be worth exploring the function of FBXO30-KIF11 interactions in cancers." (PMID 38672404, 2024). "In breast cancer, suppressing PI3K/AKT and MAPK/ERK might partially explain the cadherin switch mediated by the downregulation of KIF11." (PMID 38672404, 2024). "Currently, KIF23 and KIF11 are under investigation as TNBC drug targets; KIF11 inhibition was previously shown to stall the tumor growth of breast cancer xenografts, while KIF23 drove TNBC migration, proliferation, and the metastasis-promoting epithelial–mesenchymal transition in vitro." (PMID 39409999, 2024). "In TCGA‐BRCA‐set 2, mRNA expression levels of KIF11 were significantly higher in aggressive molecular subtypes such as triple‐negative breast cancer (TNBC) than in normal‐like or LumA breast cancer." (PMID 32346924, 2020). "The levels between KIF11 and miR‐30a present a significantly negative correlation in breast cancer databases." (PMID 32346924, 2020). "In TCGA‐BRCA‐set 2, radiotherapy significantly improved the OS of T2 breast cancer patients with KIF11‐low expression but not with the KIF11‐high expression." (PMID 32346924, 2020). "By comparing the RRM2 and KIF11 expression heat map derived from the UCSC Xena web-based tool, it was confirmed that RRM2 expression gradually elevated with increasing KIF11 transcript level, which was determined among a 50-gene qPCR assay (PAM50) breast cancer subtypes in TCGA database." (PMID 30898978, 2019). "Moreover, six hub genes were selected and validated in clinical sample for further analysis owing to the high degree of connectivity, including CDK1, CCNA2, TOP2A, CCNB1, KIF11, and MELK, and they were all correlated to worse overall survival (OS) in breast cancer." (PMID 31428132, 2019). "Unlike CCNB1, CCNA2, and CDK1, currently, the remaining genes (TOP2A, KIF11, and MELK) are not found to be associated with cell cycle; their dysfunctions might still affect the progression and prognosis of breast cancer." (PMID 31428132, 2019). "However, the inhibition of KIF11 obtained with two small synthetic molecules different from K858 showed pronounced antitumor activity in xenograft mice with breast cancer without determining any signs of peripheral neuropathy, as is common with other microtubule-targeting anticancer compounds." (PMID 35312942, 2022).
breast carcinoma (continued). "Our population study demonstrated that chemotherapy significantly improved the OS of stage II breast cancer patients with KIF11‐low expression in NKI dataset (logrank P = .004; HR = 0.23; 95% CI, 0.07‐0.63) rather than with the KIF11‐high expression (logrank P = .59; HR = 0.82; 95% CI, 0.38‐1.69)." (PMID 32346924, 2020).